INS (insulin)
Diseases named in the same sentence as INS in open-access papers (continued):
Sharing a sentence is not in itself a finding about the gene and the disease.
type 2 diabetes (continued). "However, the relationships between cortisol or aldosterone levels and insulin secretion and/or resistance in patients with untreated type 2 diabetes remain unclear." (PMID 40296149, 2025). "Interestingly, insulin’s action on glycogen synthesis was robust in three men with type 2 diabetes." (PMID 38814443, 2024). "Intra-islet crosstalk has become a focus area to fully understand the regulation of insulin secretion and impaired β-cell function in type 2 diabetes (T2D)." (PMID 39280605, 2024). "Thus, it is currently unclear whether magnesium supplementation can improve insulin sensitivity in people with type 2 diabetes and a low magnesium concentration." (PMID 37922013, 2024). "Thus, symptoms of depression follow not only as a consequence of type 2 diabetes but may contribute to its progression as well by increasing resistance to insulin." (PMID 39579357, 2024). "Phascolarctobacterium has been significantly reduced in patients with type 2 diabetes mellitus (T2DM), with its abundance negatively correlated with body fat percentage and positively correlated with insulin sensitivity." (PMID 39394090, 2024). "Thiazolidinediones (TZDs), represented by pioglitazone (PGZ) and rosiglitazone (ROSI) agents, are a class of oral insulin-sensitising agents used to manage type 2 diabetes mellitus, or T2DM." (PMID 38393619, 2024). "Longer duration of type 2 diabetes (>5 years) was associated with increased risk of mortality (HR 2.55–2.96, depending on fracture site) and there was a non-significant increase in mortality risk with insulin use (although numbers of participants were small)." (PMID 38761257, 2024). "Similarly, another analysis demonstrated that rtCGM was likely to be cost-effective compared with SMBG in a type 2 diabetes population receiving insulin therapy, with HbA1c reduction and QoL benefit from reduced fingerstick testing being the main drivers of the outcomes observed." (PMID 38951212, 2024). "In conclusion, this study confirmed that the use of isCGM could, due to its effectiveness and safety, be considered a useful tool for improving overall glycaemic control in patients with type 2 diabetes who are being treated with non-insulin or basal insulin therapy." (PMID 38337336, 2024). "Therefore, it appears that GL may serve as a relatively stable predictor, less influenced by the drugs currently taken for the treatment of type 2 diabetes that focus on insulin secretion." (PMID 38879006, 2024). "However, we and others have recently shown that insulin treatment remains an independent predictor for fractures, even after type 2 diabetes duration, glucose management and vascular complications are accounted for, and hence the roles of direct insulin effects and falls need to be clarified." (PMID 38761257, 2024). "The findings from animal studies showing improved insulin synthesis and sensitivity, increased expression of GLUT4, and protection of pancreatic B cells against oxidative stress and damage further support the potential role of bilirubin in reducing the risk of type 2 diabetes." (PMID 38195551, 2024). "Type 2 diabetes mellitus (T2DM) is a chronic metabolic disorder characterized by insulin resistance and insufficient insulin production, leading to elevated blood glucose levels." (PMID 38832149, 2024). "Thus, in conditions such as insulin resistance or early type 2 diabetes, increased insulin levels likely contribute to enhanced sympathetic activity at rest and during exercise and may play a potentiating role in the development of hypertension in MetS." (PMID 38337589, 2024). "The pathogenesis of type 2 diabetes is complex, encompassing genetics, lifestyle, environmental factors and other unknown influences, resulting in reduced ability of insulin to regulate blood sugar, which is accompanied by functional defects of pancreatic islet beta cells." (PMID 39737156, 2024).
type 2 diabetes (continued). "Interestingly, in patients with type 2 diabetes, the rate of depression was higher among those treated with insulin and oral medications compared to those taking only oral medications, and highest in patients treated with insulin alone, with odds ratio (OR): 1.59 (95%CI: 1.41–1.80, p < 0.001)." (PMID 39598055, 2024). "Type 2 diabetes mellitus (T2DM) is a chronic metabolic disorder characterized by persistent hyperglycemia resulting from impaired insulin secretion or resistance." (PMID 39655132, 2024). "In a recent study, the prevalence of IAH in patients with type 1 diabetes (T1DM) was 17%, and in patients with type 2 diabetes (T2DM) treated with insulin, it was 9.7%." (PMID 39273732, 2024). "Hence, it remains uncertain whether bariatric surgery might restore the beta-cell function of patients with insulin-treated type 2 diabetes." (PMID 38589596, 2024). "Type 2 diabetes mellitus (T2DM) is a chronic metabolic disorder characterised by hyperglycaemia due to defective insulin production and/or action." (PMID 38276562, 2024). "We formed four study groups: type 1 diabetes (T1D) and type 2 diabetes (T2D)‐diagnosed people who were further divided into prevalent or naïve users (start of insulin use before or after January 1, 2012)." (PMID 38273701, 2024). "Maturity-onset diabetes in young people is characterized by an early onset of hyperglycemia, typically before the age of 25 years, and it is associated with impaired insulin secretion with little or no disruption in insulin function." (PMID 39199594, 2024). "PTDM shares many characteristics with type 2 diabetes mellitus (T2DM), such as impaired insulin release and impaired suppression of glucagon release." (PMID 38352660, 2024). "In an 8-week study using low-dose liraglutide (0.6 mg/day) in patients with type 2 diabetes no weight or fat loss was produced, but both fasting and postprandial glucose were substantially reduced, but neither fasting nor postprandial insulin (or C-peptide) response was increased." (PMID 38890501, 2024). "Thanks to the advance of 16S rRNA and metagenome sequencing technology, the influence of the gut microbiota on type 2 diabetes mellitus (T2DM), including its participation in glucose regulation and insulin sensitivity, has been recognized." (PMID 39355267, 2024). "However, our study shows that independent of genetics, obesity increases insulin secretion compared to leaner individuals, a phenomenon linked to the development of type 2 diabetes." (PMID 39334836, 2024). "Furthermore, the secretory capacity of pancreatic β cells in Japanese patients is lower than in European and American patients due to the fact that the pathology of Japanese patients with type 2 diabetes is affected by early-phase impairment of insulin secretion." (PMID 38839813, 2024). "Type 2 diabetes mellitus (T2DM) primarily arises from cells that inadequately respond to insulin, resulting in elevated levels of blood sugar." (PMID 38612872, 2024). "Indeed, exogeneous administration of apelin lowered blood glucose levels in normal weight and obese insulin-resistant mice, thereby shedding light at the potential therapeutic implications of apelin in metabolic diseases such as type 2 diabetes mellitus (T2DM)." (PMID 38806473, 2024). "Type 2 diabetes mellitus (T2DM) is a chronic condition characterized by elevated blood glucose levels due to dysfunction in β-cell biology and impaired insulin function." (PMID 39125295, 2024). "However, among those with type 2 diabetes, significant (>20%) risk was associated with low BMI (<25 kg/m2), long type 2 diabetes duration (≥15 years), insulin treatment and absence of physical activity." (PMID 38761257, 2024). "Insulin resistance (IR) is the weakening of the responsiveness and sensitivity of tissues to physiological insulin levels, which can lead to metabolic abnormalities and continued progression to type 2 diabetes mellitus (T2DM) and MetS." (PMID 38468310, 2024).
type 2 diabetes (continued). "Although therapeutic inertia seems to affect all elements of the treatment cascade for type 2 diabetes (T2D), insulin initiation and intensification are still the key treatment steps most often affected." (PMID 38116986, 2024). "Type 2 diabetes mellitus (T2DM) is a metabolic disorder characterised by the inability of the body to use insulin properly." (PMID 38783557, 2024). "In these cost-effectiveness studies, all participants were patients with T2DM, most of whom were adults with HbA1c level greater than 7% or non-insulin-treated type 2 diabetes." (PMID 39639901, 2024). "Type 2 diabetes mellitus (T2DM) is a metabolic disease characterized by persistent hyperglycaemia secondary to insufficient insulin secretion and/or insulin resistance." (PMID 39160573, 2024). "Whether intrapancreatic ectopic fat is associated with reduced insulin secretion and increased risk of type 2 diabetes is still debated, with some but not all studies suggesting an association between pancreas steatosis and β-cell function." (PMID 37934800, 2024). "Ultra-long-acting insulin: An example would be insulin degludec.​​ It is a new ultra-long-acting insulin analog with a flat plasma glucose-lowering effect lasting for ~40 hours, suitable for meeting basal insulin requirements in patients with type 1 and type 2 diabetes." (PMID 39734941, 2024). "Studies have shown that inflammasomes can directly or indirectly affect insulin signaling pathways, contributing to the development of IR and type 2 diabetes mellitus (T2DM)." (PMID 38542170, 2024). "MET has been used as a staple in the treatment of type 2 diabetes mellitus (T2DM) for an extended period because of its ability to enhance the sensitivity of peripheral tissues to insulin and reduce its circulating levels." (PMID 38397951, 2024). "Moreover, SIRT5 may regulate the transcription of pancreatic and duodenal homeobox 1 (PDX1) via H4K16 deacetylation, to participate in pancreatic β−cell proliferation and insulin secretion in type II diabetes." (PMID 39372420, 2024). "Type 2 diabetes mellitus (T2DM) is more prevalent and occurs when the body produces insulin but is unable to use it effectively." (PMID 38555434, 2024). "A number of key studies have suggested that GIP might promote weight gain: global germline GIPR knockout mice on a HFD display reduced body weight and maintain insulin sensitivity, whilst in patients with type 2 diabetes (T2D), the insulinotropic effect of GIP is impaired." (PMID 38653401, 2024). "Furthermore, the difference in plasma insulin levels between people with type 1 and type 2 diabetes and their control groups during the experiments may be a limitation." (PMID 38376580, 2024). "Type 2 Diabetes Mellitus(T2DM), a metabolic disorder characterized by hyperglycemia resulting from insulin resistance and inadequate insulin secretion, has become a global epidemic." (PMID 38532421, 2024). "Despite the fact that the GIP hormone was the first insulin-stimulating factor discovered in the 1960s, it demonstrated an impaired insulinotropic effect in patients with type 2 diabetes mellitus (T2DM), disappointing incretin enthusiasts." (PMID 39496023, 2024). "Studies have shown that type 2 diabetes (T2DM) and childhood obesity may be related to excessive niacin intake, and excessive iron is a risk factor for T2DM patients, affecting most of their basic functions to reduce insulin secretion and insulin resistance." (PMID 39064814, 2024). "People with prediabetes or impaired glucose tolerance have a diminished first phase of secretion, while those with established type 2 diabetes (T2D) lose the first phase and show reduced second-phase insulin secretion." (PMID 38924394, 2024).
type 2 diabetes (continued). "The low proportion of insulin pump therapy in people with type 2 diabetes (0.7 %) is in line with the results of an study of diabetologists in 2023 regarding new technologies in their facilities, according to which a pump is only used in around 0.4 % of people with type 2 diabetes." (PMID 39081469, 2024). "Furthermore, SHR rats that were maintained on a high-fat diet and were developing type II diabetes (SHRDI) manifested body-weight loss, hyperglycemia, reduced plasma insulin levels, decreased myocardial and brain capillary vascularization, and enhanced oxidative stress." (PMID 38279313, 2024). "The similarities in metabolic signature between liability to type 2 diabetes and fasting insulin, but not other glycemic traits, imply signals associated with type 2 diabetes liability are likely the result of elevated insulin in response to insulin resistance instead of overall hyperglycemia." (PMID 38459184, 2024). "FFA1 signaling induced by LCFAs in pancreatic β cells can facilitate insulin secretion, making it a promising drug target for type 2 diabetes mellitus (T2D)." (PMID 38198545, 2024). "Recent studies have demonstrated a broader impact of PA on metabolism than previously suggested, including impaired insulin secretion and sensitivity, as well as type 2 diabetes mellitus (T2DM)." (PMID 39726840, 2024). "Finally, bioactive substances included in whole grains may help to enhance insulin sensitivity and slow the development and progression of type 2 diabetes by reducing oxidative stress, inflammatory cytokine transcription, and subclinical inflammations." (PMID 38998619, 2024). "Therefore, exercise training promotes an enhanced hepatic insulin sensitivity in individuals with obesity and improved hepatic insulin sensitivity and suppression of hepatic glucose production in individuals with type 2 diabetes." (PMID 38981607, 2024). "This PNI view highlights how INS operates at the intersection of metabolic, immune, neural, and endocrine pathways, emphasizing its relevance in the context of Type 2 Diabetes (T2DM)." (PMID 39595105, 2024). "The utility of SMBG in daily life is evident in insulin-treated patients with type 1 (T1D) and type 2 diabetes (T2D)." (PMID 37996773, 2024). "Type 2 diabetes mellitus (T2DM) is a condition that affects the individual’s ability to regulate insulin and glucose levels." (PMID 37980298, 2024). "Cafestol did not improve insulin sensitivity or glucose tolerance in this study but might still contribute to the observed inverse association between coffee consumption and type 2 diabetes." (PMID 39408200, 2024). "The pre-liminary therapeutic effect on high-fat-fed type 2 diabetic mice; Results: When the fucoidan/protamine mass ratio was 10:3 (w/w), the particle size and zeta potential were 140.83 ± 1.64 nm and −48.13 ± 0.61 mV.The encapsulation efficiency of insulin was 62.97 ± 0.59%." (PMID 39458652, 2024). "The aim of this systematic review and meta-analysis was to examine the effects of plant-based diets on markers of insulin sensitivity in people with overweight/obesity, prediabetes, or type 2 diabetes (T2D)." (PMID 38999858, 2024). "It is reported that melatonin (MLT) plays a protective role against type 2 diabetes mellitus (T2DM) through regulation of glucose metabolism in animals and patients via changes in insulin secretion and leptin production." (PMID 39564526, 2024). "Thus, it is still uncertain whether, and to what extent, disruptions in brain insulin circuits contribute to abnormal glucose metabolism (e.g. in type 2 diabetes)." (PMID 38363340, 2024). "Type 2 diabetes mellitus (T2DM) is a chronic metabolic disorder characterised by insulin resistance (IR), elevated blood glucose levels, and impaired insulin secretion." (PMID 38424257, 2024). "Type 2 diabetes mellitus (T2D) is a widespread chronic metabolic disease characterized by insulin resistance and decreased insulin production, resulting in elevated blood glucose levels." (PMID 39200152, 2024).
type 2 diabetes (continued). "However, the rs3842729 polymorphism (INS) does not directly affect the risk of obesity or type 2 diabetes (T2D), although elevated insulin concentrations have been observed in obese and diabetic patients." (PMID 38250713, 2024). "For many years, GIP was neglected as a therapeutic target compared with GLP-1, as it was relatively ineffective at stimulating glucose dependent insulin release in patients with type 2 diabetes (T2D) when infused continuously." (PMID 38653401, 2024). "Elevated BP is frequently observed in patients with type 2 diabetes mellitus (T2DM), potentially stemming from the influence of insulin resistance on vascular and renal functions." (PMID 39055471, 2024). "Numerous studies have linked mitochondrial dysfunction to the development of type 2 diabetes (T2D) by affecting glucose-stimulated insulin secretion in pancreatic beta cells and reducing oxidative phosphorylation in insulin-responsive tissues." (PMID 39659613, 2024). "Understanding nutrient-induced insulin secretion is important in the context of type 2 diabetes (T2D) and emerging studies linking hyperinsulinemia with a range of maladies, including cancer." (PMID 38959864, 2024). "However, under the sustained hyperglycaemic conditions that occur in type 2 diabetes, the continual demands of insulin production lead to glucotoxicity and apoptosis of beta cells (and possibly other islet cell types), further exacerbating the type 2 diabetes condition." (PMID 38967666, 2024). "Moreover, miR-29 variants, such as miR-29a-3p and miR-29b-3p, are linked not only to gut health but also to systemic conditions like sarcopenia, frailty, and type 2 diabetes, where elevated miR-29 expression affects insulin resistance, glucose homeostasis, and inflammation." (PMID 39683426, 2024). "European women who develop GDM may also be more insulin resistant and at higher risk of developing type 2 diabetes compared with European women without GDM." (PMID 38599878, 2024). "Therefore, they tested whether initiating a very-low-caloric diet (VLCD; 600 kcal/day) for 8 weeks in 11 subjects with type 2 diabetes could normalize the insulin sensitivity of the liver and restore the normal acute insulin response of the pancreas." (PMID 38791525, 2024). "Notably, a randomized controlled clinical trial found that supplementation with 10 g/d of RD in women with type 2 diabetes led to significant decreases in fasting insulin, HOMA-IR, IL-6, TNF-α, malondialdehyde, and endotoxin concentrations compared with the placebo group." (PMID 39481540, 2024). "The results of this study support the hypothesis that SGLT2i and GLP1-ra may have a beneficial role in preventing the development of DMO in individuals with type 2 diabetes taking insulin, but due to the study design they do not establish a causal link." (PMID 38584180, 2024). "In addition, the recent advances in GLP-1 agonists and associated medications might have allowed for certain individuals with type 2 diabetes to achieve insulin independence, further lowering the number of potential users identified." (PMID 39685759, 2024). "Vitamin D is involved in the pathogenesis of type 2 diabetes mellitus (T2DM), with a positive correlation of vitamin D concentrations with insulin sensitivity index and beta cell function." (PMID 38674789, 2024). "Moreover, RvD1 treatment has been found to increase levels of activated AMPK in the adipose tissues and to enhance insulin sensitivity via Akt phosphorylation, a downstream target of the insulin signaling pathway, potentially alleviating type 1 and type 2 diabetes in rats." (PMID 39273541, 2024). "Type 2 diabetes mellitus (T2DM) is a metabolic disorder characterised by high blood sugar resulting from poor insulin secretion, action or both." (PMID 37505610, 2023).